C5AR1 (complement C5a receptor 1)
Diseases named in the same sentence as C5AR1 in open-access papers (continued):
Sharing a sentence is not in itself a finding about the gene and the disease.
infection (continued). "This is contrary to previous findings that infection with the opportunistic pathogen S. aureus stimulates IL‐8 production in nasal and intestinal epithelial cells, and activates C5AR1 to stimulate the production of IL‐1β in blood." (PMID 38666460, 2024). "Considering that the site of infection was in the right flank of the mice, it is unsurprising that there was a reduction in C5ar1 expression in the bone marrow on day 3 after BCG vaccination." (PMID 39768135, 2024). "The complement components C3a/C5a and the cognate anaphylatoxin receptors C3aR and C5aR1 have well-defined and broad roles in inflammation and induction of the adaptive immune response to infection." (PMID 37855623, 2023). "At a low dose (1x105) of infection, C5aR1-/- mice showed comparatively more mortality than the WT mice, but the difference was not significant." (PMID 36211424, 2022). "Confirming the observations made above, infection with all three L. major induces (cluster 1) neutrophil recruitment, myeloid activation, and production of cytokines/chemokines (e.g. Trem1, Trem3, C5ar1, Ltf, Ptgs2, Ccl2, Ccl12, Ccl17, etc.)." (PMID 34972189, 2021). "In this simple, but yet effective way of selecting CD45+C5aR1+ cells, S. aureus can specifically target neutrophils in an infection environment." (PMID 32351474, 2020). "The frequencies of IL-12p40+ CD8α+ and CD11b+ DCs increased to a similar extent after infection in wt and C5ar1−/− mice." (PMID 32733463, 2020). "In contrast to IL-23, IL-27 serum levels sharply increased after infection in wt and to a much lower extent in C5ar1−/− animals." (PMID 32733463, 2020). "In the search for mechanisms underlying the impaired resistance of C5ar1−/− mice to T. gondii infection, we monitored IL-12p40, and IFN-γ serum levels during the first 7 days after infection." (PMID 32733463, 2020). "The frequency of IFN-γ+ NKT cells increased modestly in response to infection in wt and C5ar1−/− mice." (PMID 32733463, 2020). "The number of IFN-γ+ CD8− T cells after infection in wt or C5ar1−/− mice was 5- to 10-fold higher than that of IFN-γ+ NK or NKT cells and 2- to 3-fold higher than that of IFN-γ+ CD8+ T cells." (PMID 32733463, 2020). "Similar to the frequency, we found a strong increase in the number of IFN-γ+NK cells after infection, both in wt and in C5ar1−/− mice." (PMID 32733463, 2020). "The IL-12p40 concentration steadily increased after infection and reached a maximum of 6.2 ± 1.96 (wt) or 6.98 ± 2.67 ng/ml (C5ar1−/−) 5 days after infection in both mouse strains." (PMID 32733463, 2020). "We determined the kinetics of C5a generation in the serum of wt and C5ar1−/− mice during the acute phase of infection." (PMID 32733463, 2020). "Taken together, we found that only C5ar1−/- mice showed reduced neutrophil responses to Nme whole blood infection, whereas C3ar1−/- and C5ar2−/- neutrophils responded comparably to those from WT mice." (PMID 31274379, 2019). "Our previous study showed that mice lacking C5aR1 mounted a significantly weaker cytokine response during N. meningitidis sepsis than WT mice, indicating a positive modulation of cytokine release by C5aR1 during infection." (PMID 31274379, 2019). "This favorable outcome stemmed from an ameliorated inflammatory cytokine response to N. meningitidis in C5ar1−/− mice in both in vivo and ex vivo whole-blood infections." (PMID 29362231, 2018). "In order to test the feasibility of exploiting the protective effect of C5aR1 blockade for therapy in humans, we conducted infection experiments in lepirudinized whole blood from healthy volunteers." (PMID 29362231, 2018). "The fact that C5aR1 therapeutic inhibition performed with PMX205 treatment enhanced survival of the mice even when it was administered after infection makes C5aR1 an exciting candidate for adjuvant treatment." (PMID 29362231, 2018).
infection (continued). "In order to determine how C5aR1 engagement influences the neutrophil response to N. meningitidis, we next conducted ex vivo infections with lepirudinized mouse whole blood." (PMID 29362231, 2018). "This powerful anaphylatoxin can recruit phagocytes, such as microglia, to sites of infection or injury via its G-protein-coupled receptor C5aR1, as reviewed in." (PMID 28078911, 2017). "We detected the expression of C5aR1 in renal tract epithelium and the presence of C5a in both kidney tissue and urine, and C5aR1 and C5a upregulation following infection." (PMID 29263309, 2017). "To determine the role of C5aR1 in APN, we induced the infection in WT and C5aR1–/– mice, and then assessed renal bacterial load and tissue destruction up to 72 hpi." (PMID 29263309, 2017). "We also examined gene expression of several major extracellular matrix and cytoskeletal proteins in kidneys from WT and C5aR1-/- mice at day 14 and day 56 after infection using semiquantitative reverse transcriptase polymerase chain reaction." (PMID 27370410, 2016). "We therefore assessed the renal histopathology of infected WT and C5aR1-/- mice at different stages of infection." (PMID 27370410, 2016). "Immunohistochemistry showed that when compared with WT, C5aR1-/- kidneys had lower numbers of CD45+ cells (day 2 after infection) and F4/80+ cells (day 14 after infection) than WT kidneys, which is in agreement with the results of flow cytometry analysis." (PMID 27370410, 2016). "In contrast, gene expression of antifibrogenic factor (hepatocyte growth factor) was significantly higher in C5aR1-/- mice than in WT mice at day 2 and day 14 after infection." (PMID 27370410, 2016). "We also assessed renal function in WT and C5aR1-/- mice after infection by measuring blood urea nitrogen (BUN) levels." (PMID 27370410, 2016). "While only C5aR1 is involved in bacterial clearance, both C5aR1 and C5aR2 seem to be important for the orchestration of the inflammatory response during infection." (PMID 26512700, 2015). "As we used a murine infection model to investigate the role of C5aR1 and C5aR2 in the host response to S. aureus in this study, we first determined the expression pattern of both anaphylatoxin receptors on murine neutrophils." (PMID 26512700, 2015). "As high serum levels of pro-inflammatory cytokine IL-6 have been shown to contribute to severity of S. aureus infection, we determined the levels of serum IL-6 in wild type, C5aR1−/−, and C5aR2−/− mice at 24 h after intravenous infection with S. aureus." (PMID 26512700, 2015). "Here, we used a well-established EV-A71 infection mouse model coupled with in vitro and human experiments to investigate complement activation in astrocytes after EV-A71 infection and to determine whether inhibition of the C5a–C5aR1 axis enhances survival." (PMID 39679722, 2025). "Thus, inhibiting the C5a–C5aR1 axis has emerged as a potential therapeutic strategy to mitigate CNS injury induced by EV-A71 infection." (PMID 39679722, 2025). "Given that CPDI-02 is expected to be cleared more quickly after SQ administration than IM administration, it is possible that curative treatment requires a more sustained localization of CPDI-02 at the site of infection than prophylactic treatment to sufficiently activate C5aR1-bearing cells." (PMID 39771599, 2024). "C5aR1 is the receptor for complement component 5a (C5a), an anaphylatoxin with potent proinflammatory and chemotactic properties which is rapidly produced by the complement system during the early acute stages of inflammation and infection." (PMID 39476960, 2024). "To test this hypothesis, we infected C57BL/6 wt and C5ar1−/− mice i.p. with cysts of the T. gondii type II strain ME49 and determined complement activation, susceptibility to infection, and parasite burden." (PMID 32733463, 2020).
infection (continued). "At 5 d after the infection, C5aR2 was only significantly upregulated in the liver of infected males compared to the saline group (p = 0.02), while C5aR1 expression in the liver was consistently upregulated in both sexes (p < 0.0001 in males and p = 0.002 in females)." (PMID 32373108, 2020). "The reduced IL-27 serum levels in C5ar1−/− animals during the acute stage of infection might explain the increased numbers of CD8+ and CD8−TH cells in the spleen of such mice as compared with wt animals." (PMID 32733463, 2020). "Thus, it is possible that sustained upregulation of C3aR and C5aR1 in the brain after Toxoplasma infection is part of the defense against infection-induced damages in the CNS." (PMID 33613523, 2020). "However, when we determined IL-12p70 on day 7 after infection, we found a significantly lower cytokine production in C5ar1−/− as compared with wt mice." (PMID 32733463, 2020). "If so, it would add further value to the use of a C5aR1 antagonist in AD, avoiding the systematic suppression of NLRP3, which could lead to susceptibility to infection." (PMID 33239010, 2020). "Furthermore, plasma levels of inflammatory mediators interleukin-6 (IL-6), CXCL-1, and tumor necrosis factor (TNF) were significantly lower in C5ar1−/− mice than in WT mice at 12 h of infection." (PMID 29362231, 2018). "Thus, our aim was to assess the influence of TLR2 and the anaphylatoxin receptors, C3aR1 and C5aR1, during infection with scrapie strain 22L." (PMID 30596651, 2018). "When proposing systemic C5aR1 antagonist administration, it is important to consider the possibility that the recruitment of leukocytes into areas of infection may be dampened." (PMID 28078911, 2017). "Ex vivo and in vitro studies showed that under infection conditions, C5a/C5aR1 interaction upregulated the production of proinflammatory and profibrogenic factors by renal tubular epithelial cells and monocytes/macrophages, whereas the phagocytic function of monocytes/macrophages was down-regulated." (PMID 27370410, 2016). "This was associated with reduced renal leukocyte infiltration specifically for the population of Ly6Chi proinflammatory monocytes/macrophages and reduced intrarenal gene expression of key proinflammatory and profibrogenic factors in C5aR1-/- mice following infection." (PMID 27370410, 2016). "To test this hypothesis, we compared the levels of CXCL1 in kidneys homogenates of C5aR1−/− and C5aR2−/− mice with that of wild type mice at 12 h of infection." (PMID 26512700, 2015). "In this study, although the level of IL-6 in the middle ear was statistically lower in C5ar1−/− than WT mice, the high level of IL-6 on day 1 post Spn infection in the coinfection cohort might be attributed to the modulation of C5L2." (PMID 24740152, 2014). "However, both CPN and CPB are important during infection, where they may dampen C5aR1-mediated inflammation by generating low-affinity C5a desArg." (PMID 40122920, 2025). "Furthermore, infection induced the expression of C3aR (C3ar1) and C5aR1 (C5ar1)." (PMID 33613523, 2020). "Furthermore, during the infection, the presence of C5 and its receptor C5aR1 may represent a double-edged sword." (PMID 31687410, 2019). "Besides contributing to control systemic or local infection, the inflammatory properties observed during C5 activation and the participation of receptors such as C5aR1 may be responsible for local tissue damage." (PMID 31687410, 2019). "In addition, compared with WT, C5aR1-/- kidneys had a lower Ly6Chi population and reduced ratios of Ly6Chi to Ly6Clo populations within the MO/MΦs (Ly6G-CD11b+) compartment at both day 2 and day 14 after infection." (PMID 27370410, 2016). "However, C5aR1-/- mice had significantly lower bacterial colony counts in the kidneys at all time points after infection (day 2, day 4, and day 56) and in the bladder at day 2 and day 14 after infection compared with WT mice." (PMID 27370410, 2016).
infection (continued). "The interaction of VDBP with C5AR1 and C3 suggests that it has a role in inflammation, enhancing the chemotactic activity of complement 5a for neutrophils and activating macrophages, critical for the establishment of the early infection and subsequent propagation." (PMID 25276097, 2014). "Through western blot analysis, we observed that EV-A71 infection resulted in the upregulation of GFAP, C3, and C5aR1 expression in a time-dependent manner." (PMID 39679722, 2025). "C5aR1 activation can directly trigger the activation of NKT and NK cells, with NKT cells guiding NK cells to the site of infection and forming a unique cytokine profile." (PMID 41373839, 2025). "Here, we investigated the complement anaphylatoxin, C5a, during the early lung stage of infection with Nippostrongylus brasiliensis in C57BL/6J wild type and C5aR1-/- mice." (PMID 39628481, 2024). "The burden of viable parasites in the lungs was mitigated in C5aR1-/- mice, compared to C57BL/6J mice 48 hours post-infection." (PMID 39628481, 2024). "The homology between C5aR1 and C5aR2, and new proposed link to cGAS-STING signalling, provide rationale for further investigations C5aR2 in other infection scenarios." (PMID 38067135, 2023). "Two months post-infection, CFB, C3, C3aR, and C5aR1 expression remained higher than in controls, while CFP upregulation was transient." (PMID 33613523, 2020). "While the initial increase in IFN-γ production was similar between wt and C5ar1−/− mice, we found significantly lower IFN-γ serum concentrations 7 days after infection." (PMID 32733463, 2020). "Here, we identified a critical role for C5a/C5aR1 axis activation in CD8α+ splenic DCs resulting in IL-12 and subsequent IFN-γ production from NK cells during the first week after infection, eventually controlling parasite proliferation and persistence." (PMID 32733463, 2020). "Bacterial titers of Spn in the middle ear lavage fluid samples from C5ar1−/− cohorts infected with both IAV and Spn were significantly lower than in samples from WT mice at 24, 48, and 72 h post Spn infection (P<0.05)." (PMID 24740152, 2014). "Notably, EV-A71 infection led to activation of the C5a–C5aR1 axis in U87-MG cells, and knockdown (siC5aR1) or blockade (PMX53) of C5aR1 significantly suppressed EV-A71-induced astrocyte activation and proinflammatory cytokine (e.g., CXCL1) production." (PMID 39679722, 2025). "In addition, the complement receptor C5aR1, a prototype G protein-coupled receptor (GPCR) involved in inflammatory signaling, was significantly upregulated during infection." (PMID 41294830, 2025). "In contrast, a significant increase in C5aR1 expression was observed after infection with the Colonizing strain but not with the VVC strain." (PMID 40985395, 2025). "The IL-6 levels also increased with the time of infection but did not vary between WT and complement knockout (C3-/- and C5aR1-/-) mice groups." (PMID 36211424, 2022). "Chimera studies suggested that C5aR1 on renal cells plays a more prominent role in this model because an absence of C5aR1 on renal cells conferred better protection from infection when compared with an absence of C5aR1 on myeloid cells." (PMID 29263309, 2017). "Flow cytometry analysis of renal cell suspensions showed that when compared with WT, C5aR1-/- kidneys had lower numbers of leukocytes (CD45+) at day 2 after infection and a lower proportion of MO/MΦs (Ly6G-CD11b+) within CD45+ cells at day 14 after infection." (PMID 27370410, 2016). "However, C5aR1-/- kidneys had a similar proportion of neutrophils (Ly6G+) within CD45+ cells compared with WT kidneys at day 2 and day 14 after infection." (PMID 27370410, 2016). "Unlike infection in our C5aR1-/- mice, N. brasiliensis resistance described in FVB/N hosts could not be definitively attributed to deletion of C5, as this mouse strain possessed numerous other gene mutations." (PMID 39628481, 2024).
infection (continued). "The extracellular expression of C5aR1 on NK cells from preterm infants without infection (median-MFI = 3263) was significantly higher compared to infants with EOS or born to mothers with AIS (median-MFI = 2299) (Mann–Whitney test p = 0.009), especially on the CD56dim CD16- subset." (PMID 37373467, 2023). "Importantly, we found upregulation of Nos2 mRNA expression in the brain of wt but not C5ar1−/− mice during early infection in comparison to the naïve state." (PMID 32733463, 2020). "Interestingly, we found a significant increase in IL-27 serum concentrations in wt but not in C5ar1−/− mice after infection." (PMID 32733463, 2020). "Also, mice lacking C5aR1 and C3aR died 12 days after i.p. infection with 20 cysts of T. gondii, whereas all wt mice survived >50 days." (PMID 32733463, 2020). "However, we observed no IFN-γ production in neutrophils from spleens of wt and C5ar1−/− mice 5 days after infection (data not shown)." (PMID 32733463, 2020). "To evaluate the contribution of C5aR1 on parenchymal and/or infiltrating cells to the development of infection, we induced UTI in 4 groups of chimeric mice generated by bone marrow transplantation of irradiated recipient mice (denoted as WT→WT, C5aR1–/–→WT, WT→C5aR1–/–, C5aR1–/–→C5aR1–/–)." (PMID 29263309, 2017). "Consistent with observations made in C5aR1-/- mice, renal histopathology, tissue inflammation/fibrogenesis, collagen deposition, and bacterial load were significantly reduced in the kidneys of PMX53-treated mice compared with in the control group at day 14 after infection." (PMID 27370410, 2016). "Elevated numbers of CD11c+MHCIIhighCD11b+ DCs in absence of C3, C3aR, and/or C5aR1 in the lung on day 6 p.i might additionally indicate decreased complement-dependent recruitment of this cell type to the infected lung at later stages of infection." (PMID 33767691, 2021). "Thus, we determined whether local C5aR1 activation affects the transcription of IFN-γ (Ifng) in the spleen and brain as well as IL-12p35 (Il12a), IL-12p40 (Il12b), IL-18 (Il18), and iNOS (Nos2) in the brain of T. gondii-infected animals on day seven after infection using RT-qPCR." (PMID 32733463, 2020). "Furthermore, most of the pro-inflammatory genes found on this array, which we have previously identified to be increased with 22L infection (such as Cxcl10, Ccl8, Tnf, IL1a, and IL1b), were similarly increased in the absence of TLR2 or C5aR1 signaling during scrapie infection." (PMID 30596651, 2018).
bacterial infection (10 papers, 2014 to 2023). "Our findings demonstrate that the specific genetic or pharmacological disruption of C5aR1 rapidly ameliorates disease by suppressing the pathogenic inflammatory response and, surprisingly, allows faster clearance of the bacterial infection." (PMID 29362231, 2018). "Although inhibition of C5 by neutralizing antibodies has been associated with increased risk of bacterial infection due to the inhibition of the formation of the membrane attack complex, the selective targeting of C5a/C5aR1 signaling may avoid harmful anaphylatoxin-induced effects." (PMID 37104043, 2023). "Recently, C5aR1 has been identified to promote bacterial infections, as it can act as a receptor for toxins including those secreted by Staphylococcus aureus." (PMID 36977592, 2023). "Functional annotation of putatively selected genes revealed that these genes were predominantly associated with immune-related functions, inclusive of genes such as C5AR1 and MYH10 (bacterial infection); ARHGEF1, ERCC2 and TRAF2 (viral infection) and IFNGR2 (both viral and bacterial infection)." (PMID 33116287, 2020).
neurodegenerative disease (9 papers, 2013 to 2025). A disorder of the central nervous system characterized by gradual and progressive loss of neural tissue and neurologic function. "In contrast, in the context of neurodegenerative diseases such as AD, C5aR1 expression has been associated with neurotoxic microglial clusters." (PMID 41261092, 2025). "However, dysregulation of the C5a-C5aR1 pathway is associated with a myriad of acute and chronic inflammatory conditions and neurodegenerative diseases." (PMID 41373839, 2025). "Thus, targeting C5aR1 has high potential for treatment of neurodegenerative diseases, and therefore is a promising candidate for clinical trials in disorders such as AD." (PMID 39147742, 2024).